SPHK1 (sphingosine kinase 1)
Diseases named in the same sentence as SPHK1 in open-access papers (continued):
Sharing a sentence is not in itself a finding about the gene and the disease.
cancer (continued). "SPHK1 expression significantly correlated with the expression of many EGFR pathway genes associated with invasion of cancer cells." (PMID 21936950, 2011). "Overexpression of sphingosine kinase-1 (SPHK1) has been demonstrated to be associated with the development and progression in various types of human cancers." (PMID 20846391, 2010). "Disruption of the axis through SPHK1 knockdown in CAFs, genetic perturbation of MALL or SDC4 in cancer cells, or adeno-associated virus-mediated SPHK1 or SDC4 knockdown in KPC (KrasLSL-G12D/+; Trp53LSL-R172H/+; Pdx1-Cre) mice significantly reduces PNI and tumor burden." (PMID 42017444, 2026). "Furthermore, the impact of these compounds on the expression levels of sphingosine kinase 1 (Sphk1), an enzyme implicated in cancer development, was investigated in MCF-7 cells." (PMID 40358625, 2025). "Hence, SPHK1/2 is the master regulator for S1P production, it has been associated with the development of many types of cancer." (PMID 39284838, 2024). "Furthermore, the influence of 1–4 on the expression levels of sphingosine kinase 1 (Sphk1), which is an enzyme implicated in cancer progression, was investigated in MCF-7 cells." (PMID 39407639, 2024). "Also, the present review discusses SphK1 gene expression among different carcinomas and associated impact on survival with elaborating the protein subcellular compartmentation, and protein–protein interactions." (PMID 38419070, 2024). "Conversely, pharmacological inhibition, genetic silencing or loss-of-function mutation of SphK1/2 could induce sphingosine and ceramide accumulation, causing growth arrest and apoptosis in different cancer cells." (PMID 37604912, 2023). "SPHK1 is a crucial member of the sphingosine kinase family participating in the regulation of numerous cancer-related bio-processes, such as cell proliferation, invasion, and angiogenesis, and is associated with prognosis in a wide range of cancers." (PMID 36672336, 2023). "This discovery is important for future SphK1-related cancer research and may have clinical implications in drug development associated with SphK1-directed cancer treatment." (PMID 36532885, 2022). "A meta-analysis has shown that increased SPHK1 expression is associated with poor prognosis in human cancers and could be a promising prognostic marker and therapeutic target in patients with malignancies." (PMID 35965565, 2022). "SPHK1 upregulation promotes chronic inflammation and colitis-associated cancer development." (PMID 35565311, 2022). "Notably, immunohistochemical (IHC) staining of human cancer tissues indicated that the presence of SphK1 in nuclei is associated with shorter disease-specific survival and cancer recurrence." (PMID 33919234, 2021). "Moreover, SPHK1 has been found to control cancer cell migration and modulate interaction of cancer cells with cancer-associated fibroblasts, contributing to tumor invasion and metastasis." (PMID 34820423, 2021). "Sphingosine kinase 1 (SphK1), a regulator of sphingolipid metabolites, involves in the process of cancer including proliferation, invasion, and metastasis and it is associated with the prognosis of various cancer." (PMID 34268882, 2021). "In a variety of cancer subtypes, SPHK1 expression has been associated with drug resistance." (PMID 33660008, 2021). "The perspective might provide novel insight into the association between SPHK1 and pyroptosis and suggest the potential target for cancer therapy." (PMID 33123153, 2020). "These molecules may be exploited as potent and selective inhibitors of SphK1 that could be implicated in cancer therapeutics after the required in vivo validation." (PMID 32526899, 2020). "Hence, targeting SphK1 by these natural compounds can be a smart therapeutic approach to manage the clinical manifestations of cancer and other SphK1 associated human pathologies." (PMID 31822735, 2019). "High SPHK1 expression has been associated with a poor prognosis in several human cancers." (PMID 31101115, 2019).
cancer (continued). "PI3K and SPHK-1 pathway have been implicated in cancer chemoresistance." (PMID 28165392, 2017). "Overexpression of SphK1 is now becoming recognized as a diagnostic marker for many cancers, however, it may only have limited value as a prognostic indicator of treatment outcome." (PMID 28869494, 2017). "SphK1/S1P is also involved in chronic intestinal inflammation-associated cancer." (PMID 29269995, 2017). "In contrast, overexpression of SphK1 is associated with increased cancer risk." (PMID 25866760, 2015). "Conversely, SphK1 inhibition (by its inhibitors), silencing (using genetic measures), or loss-of-function of mutations shall lead to depleted S1P formation, while inducing accumulation of pro-apoptotic ceramide and sphingosine, eventually causing growth arrest and apoptosis in cancer cells." (PMID 35115496, 2022). "Therefore, increased SPHK1 expression may be statistically associated with poor prognosis in cancer patients, although the certainty of evidence is low." (PMID 35126792, 2022). "In summary, although SphK1 is highly expressed in many cancer cell types, compared to its contemporary cell type, its suitability as a diagnostic or therapeutic biomarker for all cancers is still unknown." (PMID 28415564, 2017). "Functionally SphK1 is the major isoform linked with many of the hallmarks of cancer and it has historically been identified as a major driver of cancer with a shorter overall survival in many human cancer patients, contributing to chemo-resistance and poor survival." (PMID 28869494, 2017). "Numerous studies have demonstrated that upregulation of SPHK1 can promote cell proliferation and enhance the resistance to apoptosis induced by different stimuli, and that this upregulation is linked to the failure of clinical cancer therapies, such as chemotherapy and radiotherapy." (PMID 20846391, 2010). "We observed significant upregulation of SPHK1 in multiple cancers, especially in HNSC, STAD, and LIHC." (PMID 41547931, 2026). "In this pan-cancer study, we analyzed SPHK1 expression using RNA-seq data from The Cancer Genome Atlas, which includes 33 cancer types." (PMID 41547931, 2026). "Early drug development targeted SphK1 for oncology purposes; however, further studies have shown that both isoforms are involved in regulating cancer cell processes." (PMID 40006080, 2025). "Cancer cells often highly express SphK1 and produce high levels of S1P, which together promote cancer progression and metastases." (PMID 40528704, 2025). "Over‐expression of SPHK1 protein and gene expression compared to normal tissues has been observed in cancers of the bladder, oesophagus, colon, stomach, breast and ovary." (PMID 40356021, 2025). "Meanwhile, SPHK1 was involved in resistance to chemotherapy and treatment against SPHK1 has been identified as effective anti-cancer treatment for a variety of cancers." (PMID 39875359, 2025). "In contrast to SphK1, SphK2’s role in disease, and in particular in cancer, is not fully understood." (PMID 39940821, 2025). "There is a known correlation between cancer and changes in sphingolipids, particularly the production of S1P by SPHK1 and SPHK2." (PMID 41234914, 2025). "SPHK1 suppression has also been shown to reduce tumour burden in vivo for head and neck, colon, breast and intestinal cancers." (PMID 40356021, 2025). "It has been shown that many cancers are characterized by high levels of SphK1 and this is directly correlated with poor prognosis, reduced survival, and advanced tumor stage." (PMID 39940821, 2025). "Fingolimod (FTY720), an FDA-approved modulator of SPHK1, has demonstrated potential in cancer therapy by promoting anti-tumor immunity and reducing tumor growth." (PMID 41150752, 2025). "In particular, S1P/SphK1 is intrinsically involved in drug resistance; this signaling pathway protects cancer cells from chemotherapy-induced apoptosis." (PMID 39940821, 2025).
cancer (continued). "Research suggest that sphingosine kinase 1 (SphK1) plays a crucial role in metastasis and prognosis in cancer patients." (PMID 41234914, 2025). "Sphingosine kinase 1 (SK1) produces sphingosine-1-phosphate, a bioactive lipid implicated in cancer progression and other diseases." (PMID 40386399, 2025). "SphK1 has been shown to regulate tumorigenic properties and cancer progression by modulating apoptosis, autophagy, proliferation, migration, invasion, angiogenesis, and inflammation." (PMID 39940821, 2025). "In summary, by controlling S1P production, SphK1 and SphK2 tune oncogenic signaling networks; their sustained over-expression fuels the initiation and progression of multiple human cancers." (PMID 41234914, 2025). "These inhibitors attenuate the activity of SphK1 and subsequently decrease the production rate of S1P suppressing cancer cell resistance." (PMID 38419070, 2024). "In mammals, SPHK1 has been extensively studied for its role in cancer progression, particularly in promoting invasion and metastasis through the epithelial–mesenchymal transition (EMT) pathway." (PMID 39769404, 2024). "Single-cell analysis revealed high expression of SPHK1 in tumor cells (SOX2, KRT18) and cancer-associated fibroblasts (COL1A2 and MMP2) and low expression in cancer stem cells (PROM1)." (PMID 39629135, 2024). "SphK1 is aberrantly overexpressed in various cancers, including HCC, and correlates with poor prognoses." (PMID 38200582, 2024). "SphK1 has been reported as a promotor of cancer progression by activating the JAK/STAT pathway and enhancing S1PR1 expression in CC cells." (PMID 38673975, 2024). "Activation of SphK1 and S1P synthesis are responsible for growth-stimulating and pro-survival effects in normal and cancer cells." (PMID 38698424, 2024). "The high expression level of SphK1 induces cancer cell movement, migration, and invasion by controlling the movement of actin from focal adhesions to membrane ruffles and lamellipodia, which is necessary for migration." (PMID 38419070, 2024). "Our team overviewed SphK1 expression among different cancers, several resistance processes, S1P metabolism, S1P transport, S1P signaling, and SphKs inhibitors, with molecular docking for up-to-date all publicly available SphK1 inhibitors." (PMID 38419070, 2024). "The findings suggest that MP-A08, as a selective SPHK1 inhibitor, holds promise as a potential anti-cancer therapy for AML." (PMID 38399263, 2024). "In our study, we will discuss the potential inhibitory effect of several SphK1 suppressors as an adjuvant treatment against cancer to tackle chemoresistance." (PMID 38419070, 2024). "SphK1/2, “housekeeping” enzymes, are constitutively expressed and function to support the membrane metabolism in all cell types, including cancer and immune cells." (PMID 38698424, 2024). "Given the well-documented pro-cancer role of SphK1, its highly selective inhibitor, PF-543, emerges as a promising candidate for cancer therapy." (PMID 38200582, 2024). "In conclusion, the literature suggests that S1P inhibition or down-regulated SphK1 expression can be a promising approach to decrease cancer cell resistance." (PMID 38419070, 2024). "Sphingosine kinase 1 (SPHK1) is an enzyme known for its pro-survival signalling roles in cancer initiation, progression, and resistance to cytarabine chemotherapy." (PMID 38399263, 2024). "Many studies have shown that SPHK1 activation can induce cancer cell migration and that the SPHK1/S1P axis enhances the metastatic potential of cancer cells." (PMID 39767749, 2024). "Whereas cancer cells induce high expression of S1P and its SphK1/2 enzymes to increase growth, and angiogenesis." (PMID 38419070, 2024). "Based on the docking simulations, it can be concluded that SG14, SLC4011540, and SK1-5c can effectively inhibit SphK1 and are, therefore, considered potent drugs to improve the sensitivity of cancer cells towards chemotherapies." (PMID 38419070, 2024).
cancer (continued). "Previous studies have found that the expressions of SPHK1 had a positive correlation with CRC metastasis, and patients with SPHK1-positive cancer had a worse prognosis than those with SPHK1-negative cancer." (PMID 38135696, 2024). "S1P, and SphK1 overexpression are considered hallmarks of several carcinomas with involvement in several chemoresistance machineries." (PMID 38419070, 2024). "Sphingosine kinase 1 (SPHK1), one of the two identified SPHKs, regulates cancer progression, thus representing a critical player in the sphingosine-S1P balance." (PMID 36672428, 2023). "It has been shown that SPHK1 participates in the regulation of autophagy and in different aspects of malignancy including therapy resistance, cancer development, growth, and metastasis." (PMID 37190124, 2023). "Increased expression and/or activation of SphK1/2 often correlate with the poor prognosis in various human cancers." (PMID 37604912, 2023). "It has been shown that SPHK1 is upregulated in multiple types of human cancers, and the expression of SPHK1 in CRC tissue is significantly increased compared to normal colorectal tissue." (PMID 37108361, 2023). "SPHK1 is highly expressed in different types of cancers, such as human astrocytoma, CRC, and prostate cancer." (PMID 37190124, 2023). "The high expression of SPHK1 in the lung, breast, gastric, esophageal, colon, and liver cancer, as well as glioma, is closely related to the poor prognosis of patients." (PMID 36823149, 2023). "It has been demonstrated that FTY720 blocks the SPHK1/S1P/S1PR1 axis, leading to the blockade of the NF-kB/IL-6/STAT3 amplification loop and colitis-associated cancer." (PMID 36714534, 2023). "SphK1 and S1P signaling plays important roles in multiple diseases, such as cancer, diabetes and inflammation-related diseases, rheumatoid arthritis, atherosclerosis and multiple sclerosis." (PMID 36909198, 2023). "We also found that SPHK1 in the EVs of cancer patients was highly active compared with that from the healthy controls as well as from cells lines HeyA8 and OVCAR5." (PMID 35289120, 2022). "As for SphK1, it has been proved to be highly expressed in various cancer cells, such as ovarian, cervical, colon, stomach, lung and brain cancers." (PMID 35335379, 2022). "There is substantial evidence to show that SphK1 plays a critical role in many types of cancer progression, as well as many other chronic diseases." (PMID 36532885, 2022). "SPHK1 is involved in regulation of multiple cellular processes, such as cell survival, cellular migration, angiogenesis and cancer progression." (PMID 35854233, 2022). "In human biopsies, a significant increase of SphK1 activity was observed in cancer compared with normal bones." (PMID 35158767, 2022). "SPHK1 catalyzes the conversion of sphingosine to S1P, which regulates numerous cellular processes and is involved in inflammation and cancer." (PMID 36543771, 2022). "SPHK1, which produces S1P, seems to play a core role in cancer progression, although its characteristics in LAM are not clear." (PMID 36543771, 2022). "Due to the obvious statistical heterogeneity (I2 = 57.3%, P = 0.009), the random model was applied and a significant association was observed between increased SPHK1 expression and poor DFS of cancer patients (HR = 1.34, 95% CI: 1.13-1.59, P = 0.001)." (PMID 35126792, 2022). "As SphK1/S1P signaling contributes to malignant progression by controlling proliferation and metastatic potential of cancer cells, it represents a potential target for anticancer therapy." (PMID 35158767, 2022). "Overexpression of SPHK1 in cancer cells has been shown to correlate with poor survival outcome for metastatic melanoma patients treated with an immune checkpoint inhibitor such as anti-PD-1." (PMID 35565311, 2022). "To further validate this binding, we used GFP‐Trap beads to immunoprecipitate GFP‐tagged SPHK1 from cancer cells and we found that SPHK1 does indeed interact with TSG101." (PMID 35289120, 2022).
cancer (continued). "Studies have shown that the abnormal expression of SPHK1 can promote the occurrence of cancer and tumor progression." (PMID 35126792, 2022). "Then, in the downstream of sphingolipid pathways, the activity of SPHK1/S1P plays an important role in many cancers, and SPHK1 has been proven to be highly expressed in a variety of cancers." (PMID 35965565, 2022). "Hazard ratios (HRs) and 95% confidence intervals (CIs) were pooled to estimate the impact of SPHK1 expression on cancer patients' survival." (PMID 35126792, 2022). "Sphingosine kinase 1 (SphK1) is commonly overexpressed in cancer cells and correlates with poor patient prognosis in a number of tumor types." (PMID 35158767, 2022). "The relevance and consequence of individual SphK1 isoform expression, especially the longer SphK1b isoform, in cancer cells are underexplored and unclear." (PMID 36532885, 2022). "SphK1/S1P signaling is commonly upregulated in cancer cells and correlates with poor patient prognosis in a number of tumor types." (PMID 35158767, 2022). "SPHK1 is the primary enzyme for S1P synthesis, and S1P has been confirmed to contribute to physiological and pathological process in cancer cells." (PMID 36543771, 2022). "Second, SPHK1 expression can be used as a reliable biomarker to grade the prognosis of cancer patients." (PMID 35126792, 2022). "Deregulation of the S1P signaling pathway contributes to the development and progression of a variety of cancer types, and the altered expression of SPHK1 and the S1PRs are common mechanisms." (PMID 36361531, 2022). "Thus, this study demonstrated that high immunohistochemical expression of SPHK1 in cancer tissues may be associated with poor survival in human solid tumor patients, which will promote the development of a novel biomarker for the diagnosis and prognosis and targeted therapy of solid tumors." (PMID 35126792, 2022). "In priCa-1 and priCa-2 primary cancer cells, SphK1 protein levels were dramatically decreased after GNE-493 treatment (250 nM, 12 h)." (PMID 35296639, 2022). "Tissue microarrays (TMAs) showed that both SPHK1 and PD‐L1 were highly expressed in malignant tumor tissue in comparison with normal ovarian tissue and normal adjacent tissue." (PMID 35289120, 2022). "Profiling SphK1 isoform expression of patient tissue samples shows that SphK1a is detected in the liver, prostate, and breast, both in cancer and adjacent tissues." (PMID 36532885, 2022). "Collectively, such data support a role for SPHK1 in immunosuppression in different types of cancer, making it an important therapeutic target." (PMID 35289120, 2022). "As demonstrated in the representative microphotographs, a strong, immunohistochemical (IHC)-positive signal for SphK1/K2 was confirmed in both normal mucosa and cancer tissues." (PMID 35806446, 2022). "Although, upregulation of SPHK1 is reported in multiple cancers including PDAC, our transcriptome data in PDAC was less than the cut off of 2-fold change." (PMID 35854233, 2022). "PubMed, Web of Science, Embase, CNKI, and Wanfang databases were thoroughly searched for eligible studies, in which the relationship between SPHK1 expression and cancer prognosis was evaluated." (PMID 35126792, 2022). "In cancer stem cells (CSCs) or tumor-initiating cells, SPHK1 expression enhanced tumor formation via Notch activation stimulated by S1PR3 in both in vitro and in vivo studies." (PMID 35565311, 2022). "High levels of SPHK1 and CERK in nodal positive and late-stage cancer patients as well as association of high CERK expression to poor patient survival are indicative of their potential as diagnostic and prognostic biomarkers." (PMID 36309544, 2022). "We observed significant differential expression of SPHK1 in multiple cancers compared with that of SPHK2, which suggested the global ubiquity of SPHK1 dysregulation in cancers." (PMID 36050478, 2022).